NPM1 (nucleophosmin 1)
Diseases named in the same sentence as NPM1 in open-access papers (continued):
Sharing a sentence is not in itself a finding about the gene and the disease.
viral infection (15 papers, 2012 to 2024). "NPM1 associates with viral proteins of different viruses and is implicated in various stages of viral infection." (PMID 28359267, 2017). "As in c-MYC, dramatic NPM1 expression was induced in EBV positively infected B cells after three days of viral infection, and both EBNA2 and EBNALP were implicated in the transactivation of the NPM1 promoter." (PMID 23271972, 2012). "Colocalization analysis showed that NPM1 translocates from the nucleolus to the nucleoplasm and cytoplasm during viral infection." (PMID 33073687, 2020). "Accumulated evidence implies that NPM1 seems to have co-evolved with the human viruses to facilitate diverse virus infection processes within the nucleus." (PMID 23271972, 2012). "Accordingly, we observed a pronounced induction of both c-MYC and NPM1 in EBV positively infected B lymphocytes throughout the duration of viral infection." (PMID 23271972, 2012). "As a result, NPM1 is involved in various stages of the viral life cycle, including the nuclear import of viral proteins and final assembly, making it a target for the treatment of various viral infections." (PMID 39120297, 2024). "Additionally, LYAR can directly interact with NCL and colocalize with NPM1 in nucleoli, providing a possibility for them to form a complex during virus infection." (PMID 30209172, 2018). "Thus, NPM1 seems to represent a key protein in viral infections that is hijacked by invading pathogens to facilitate infection." (PMID 26624888, 2015). "That is the case of the B23/NPM1 protein, a major target for CIGB-325 in solid tumor cells, which plays an important role as a proviral chaperone in animal and human virus infections." (PMID 35336959, 2022). "The binding of NPM1 to other proteins of PEDV and its role in viral infection remains to be further explored." (PMID 36366532, 2022). "However, at late times post-viral infection, the interaction of the newly synthesized pVII complexed to the adenovirus DNAs with TAF-III (nucleophosmin/B23/NPM1) appears to remodel viral chromatin in infected cells." (PMID 33671079, 2021). "NPM1 promotes infection by a variety of viruses, including the human immunodeficiency virus type 1 (HIV-1), Japanese encephalitis virus (JEV), adenovirus, herpes simplex virus 1 (HSV-1), Epstein–Barr Virus (EBV), and Schmallenberg virus (SBV), function at all stages of viral infection." (PMID 36366532, 2022). "Viral infection is known to impact many aspects of cellular function, and we and others have observed that localization of RNA-binding proteins and nucleolar factors is disrupted during alphavirus infection, including DDX56, nucleolin, NPM1, and fibrillarin (46 and data not shown)." (PMID 33109765, 2020).
bladder cancer (14 papers, 2007 to 2025). "Tsui and colleagues showed that the overexpression of NPM1 at the mRNA level is independently associated with the recurrence of bladder carcinoma and progression to the more advanced stage." (PMID 29221119, 2017). "Overexpression of NPM1 mRNA is independently associated with the recurrence of bladder carcinoma and progression to a more advanced stage of disease." (PMID 25779011, 2015). "For example, overexpression of NPM1 mRNA was independently associated with bladder cancer recurrence and progression to more advanced disease stages." (PMID 25663821, 2014). "In bladder cancer, NPM1 contributes to tumor development and is correlated with poor patient prognosis, larger tumor size, advanced tumor stage, and increased recurrence rates." (PMID 40705480, 2025). "The NPM1 gene was successfully silenced in three drug-resistant bladder cancer cell lines by lentivirus infection." (PMID 32411234, 2020). "In proteomic analysis of drug-resistant bladder cancer, the expression of NPM1 has been proved to be significantly different." (PMID 32411234, 2020). "The effects and proteomic bioinformatics of NPM1 gene knockout on cisplatin-resistant bladder cancer cells were analyzed by liquid chromatography-mass spectrometry (LC-MS) and gene ontology analysis (GO analysis)." (PMID 32411234, 2020). "To evaluate the value of CD40 as a biomarker in cisplatin-resistant bladder cancer, we established NPM1 silencing stable cell lines by lentivirus infection in three cisplatin-resistant bladder cancer cell lines." (PMID 32411234, 2020). "There is a positive correlation between CD40 protein and NPM1 protein in drug-resistant bladder cancer." (PMID 32411234, 2020). "Previous studies in our laboratory have shown that NPM1 can reflect specific biological behavior such as recurrence and drug resistance in bladder cancer." (PMID 32411234, 2020). "Western blot showed that the expression of CD40 in three NPM1 silencing bladder cancer cell lines was downregulated." (PMID 32411234, 2020). "The expression of CD40 and NPM1 in three NPM1 silencing bladder cancer cell lines were detected by fluorescence microscopy and Western Blot." (PMID 32411234, 2020). "In our previous experiments, it has been confirmed that the differential expression of NPM1 can reflect the oncological characteristics of cisplatin-resistant bladder cancer." (PMID 32411234, 2020). "Downregulation of NPM1 can accelerate the invasion and the growth of cisplatin-resistant bladder cancer." (PMID 32411234, 2020). "The effects of NPM1 gene knockout on cisplatin-resistant bladder cancer cells were analyzed by mass spectrometry." (PMID 32411234, 2020). "In the urogenital system, NPM1 could promote cell proliferation and migration and drug resistance in bladder cancer." (PMID 37875480, 2023). "However, as a protein only existing in cells, NPM1 has limited sensitivity as early monitoring of bladder cancer." (PMID 32411234, 2020). "The expression of NPM1 in bladder cancer cells increases when the recurrence and drug resistance of invasive bladder cancer cells increase, suggesting that NPM1 may be an important prognostic indicator of bladder cancer cells." (PMID 32411234, 2020). "Subsequent step-wise multivariate regression distilled the model to four independent predictors—NPM1 (HR = 1.42), RUNX2 (HR = 1.25), TET1 (HR = 1.41), and TIA1 (HR = 0.67)—thereby establishing a concise LLPS-related signature for risk stratification in bladder cancer." (PMID 41300366, 2025). "In addition, NPM1 can also reflect the development of cisplatin-resistant bladder cancer." (PMID 32411234, 2020). "Three cisplatin-resistant bladder cancer cell lines (T24/0.8DDP, BIU87/0.3DDP, and PUMC-91/0.6DDP) were studied, and lentivirus was used to silence NPM1 expression." (PMID 32411234, 2020). "Because NPM1 can reflect the characteristics of bladder cancer, CD40 may be a more sensitive marker for monitoring the prognosis of bladder cancer." (PMID 32411234, 2020).
gastric cancer (14 papers, 2007 to 2024). A primary or metastatic malignant neoplasm involving the stomach. "Recently, the association of the high NPM1 expression with poor prognosis was also demonstrated in bladder urothelial carcinoma, gastric cancer and glioma." (PMID 30126426, 2018). "Since NPM3 was recently described to be involved in regulating PD-L1 expression in gastric cancer through binding to NPM1 and promoting its binding to the PD-L1 promoter, we analysed PD-L1 expression at the mRNA level." (PMID 39300184, 2024). "In contrast, NPM1 protein expression is decreased in gastric cancer, inhibiting tumor proliferation and migration, and thus acting as a tumor suppressor." (PMID 37254219, 2023). "NPM1 protein expression was significantly reduced in gastric cancer samples compared to matched non-neoplastic gastric samples (P = 0.019)." (PMID 24410879, 2014).
non-small cell lung carcinoma (13 papers, 2016 to 2026). A group of at least three distinct histological types of lung cancer, including non-small cell squamous cell carcinoma, adenocarcinoma, and large cell carcinoma. "Similar to the discovery of NPM1-ALK in ALCL, the echinoderm microtubule-associated protein-like 4 (EML4)-ALK fusion gene was discovered as a cancer driver gene, which is detected in ~7% of patients with non-small cell lung carcinoma (NSCLC)." (PMID 37894456, 2023). "NSC348884 is a small molecule that disrupts NPM1 oligomerization, leading to apoptosis in AML and non-small cell lung cancer (NSCLC) cells." (PMID 41516383, 2026).
glioma (12 papers, 2015 to 2024). A benign or malignant brain and spinal cord tumor that arises from glial cells (astrocytes, oligodendrocytes, ependymal cells). "Given that both NPM1 and H1.5 have been implicated in apoptosis we decided to further study any potential interplay between these two proteins in glioma cells." (PMID 26559910, 2015). "Nucleophosmin 1 (NPM1) is another histone chaperone with elevated expression in high-grade compared to low-grade gliomas, and its overexpression improves cell survival, while NPM1 depletion leads to apoptosis and increases susceptibility to the chemotherapy agent actinomycin D." (PMID 31752169, 2019). "A reduction in NPM1 modestly sensitized glioma cells to cell death triggered by a deficiency in H1.5 suggesting that NPM1 may act in a pro-survival manner." (PMID 26559910, 2015). "The expression of NPM1 is related to the mitotic index; moreover, the overexpression of NPM1 represents a poor prognosis for glioma patients." (PMID 33628783, 2021). "This re-localization of NPM1 to the nucleoplasm of glioma cells and NSCs induced by Act D was easily detected here." (PMID 26559910, 2015). "Nucleolar NPM1 immunoreactivity was detected in tumor cells of high and low grade gliomas in all 60 cases." (PMID 26559910, 2015). "A side-by-side comparison revealed markedly elevated levels of NPM1 in glioma cells when compared to astrocytes as shown by both IF staining and IB." (PMID 26559910, 2015). "In contrast, NPM1 which is up-regulated in glioma physically interacts with NCL and increases its activity." (PMID 26108672, 2015). "Glioma cell cultures depleted of NPM1 exposed to micromolar levels of actinomycin D were more prone to cell death (apoptosis) compared to cultures retaining NPM1." (PMID 26559910, 2015). "We applied this antibody for use in immunohistochemical (IHC) analysis of NPM1 in human glioma samples." (PMID 26559910, 2015). "We conclude from these experiments that NPM1 is a suitable marker for nucleolar stress in NSCs and glioma cells." (PMID 26559910, 2015). "Next, we compared the levels of NPM1 in glioma cells U1242MG and U343MGa Cl2:6 with normal cortical astrocytes from rat." (PMID 26559910, 2015). "Cell cycle analysis by FACS using propidium iodide labeling of DNA, indicated no major change in cell cycle phase distribution in U1242MG and U251MG glioma cells when depleted of NPM1." (PMID 26559910, 2015). "We found that glioma cell apoptosis induced by Act D was significantly increased in the context of reduced levels of NPM1." (PMID 26559910, 2015). "To investigate if NPM1 silencing had any effect on glioma cell proliferation we selected three glioma cell lines that were subjected to transfection with NPM1 siRNA." (PMID 26559910, 2015). "Depletion of NPM1 in glioma cell lines resulted in less visible nucleoli and altered chromatin structure around nucleoli as seen by DAPI." (PMID 26559910, 2015). "We also wanted to determine the effect of NPM1 silencing on the glioma cells response to the more clinically relevant compounds temozolomide (TMZ) and 5-fluorouracil (5-FU)." (PMID 26559910, 2015). "It was reported that loss of NPM1 sensitized U87MG and A172 glioma cells to temozolomide (TMZ) with an increase in cell death." (PMID 26559910, 2015). "NPM1 was concentrated to glioma cell nucleoli, but a marked nucleoplasmic NPM1 staining was observed in the majority of grade IV tumors, in human glioma cell lines, as well as in undifferentiated mouse NSCs." (PMID 26559910, 2015). "A survey of The Cancer Genome Atlas data using the cBioPortal and the COSMIC databases revealed that no mutations in NPM1 have been found to date in 291 cases of high grade gliomas, according to exome and whole genome DNA sequencing." (PMID 26559910, 2015). "Enforced expression of NPM1 suppressed apoptosis in H1.5 depleted glioma cells." (PMID 26559910, 2015). "We next investigated NPM1 ́s localization in a panel of human glioma cell lines." (PMID 26559910, 2015).
glioma (continued). "We proceeded with silencing of NPM1 in the established human glioma cell lines using siRNA." (PMID 26559910, 2015). "Since NPM1 depletion also sensitizes glioma cells to Act D it might be suggested that this is due to accumulated targeting of DNA integrity rather than a specific loss of function as a consequence of a lost NPM1-H1.5 interaction, this remains to be determined." (PMID 26559910, 2015). "We hypothesized that reduced levels of NPM1 may sensitize glioma cells to cell death, while the abundant NPM1 would protect the glioma cells from death signals (apoptosis)." (PMID 26559910, 2015). "Immunohistochemical staining showed high expression of DNCH2, ARHGEF6, NPM1, and SRI, while low expression of NRGN and TM4SF2 in gliomas." (PMID 38427106, 2024). "Depletion of NPM1 had only modest effects on the viability of U251MG, U1242MG, and U343MGa Cl2:6 glioma cells, despite alterations in nucleolar morphology." (PMID 26559910, 2015). "We found that all glioma cell lines tested by us so far, including U343MGa Cl2:6, U343MG, U118MG, U178MG and U1240MG stained positive for NPM1." (PMID 26559910, 2015). "Although NPM1 was not completely silenced we conclude that the bulk of NPM1 protein is dispensable for glioma cell proliferation in the shorter term." (PMID 26559910, 2015). "While we did not observe any major effects on glioma cell proliferation and viability by NPM1 depletion only, our results suggest that NPM1 act in a pro-survival manner when cells are stressed." (PMID 26559910, 2015). "In agreement, we found that a reduction in NPM1 levels did not have any major effects on glioma cell viability or cell proliferation despite alterations in nucleolar morphology." (PMID 26559910, 2015). "However it was noted that U87MG glioma cell proliferation rate did not change significantly in response to NPM1 knockdown until after the 7th day of transfection." (PMID 26559910, 2015). "We conclude that silencing of H1.5, but not of NPM1, triggers apoptosis in glioma cell lines." (PMID 26559910, 2015). "From our experiments we could conclude that silencing of H1.5, but not NPM1, triggered apoptosis in glioma cell lines." (PMID 26559910, 2015).
melanoma (12 papers, 2008 to 2025). A malignant, usually aggressive tumor composed of atypical, neoplastic melanocytes. "In melanoma the over-expression of NPM1 has already been confirmed; it has also been reported that this protein undergoes hyperphosphorylation." (PMID 29545914, 2018). "Up-regulation of one of these genes, NPM1 (nucleophosmin), was found at both protein and transcript levels in melanoma cells, compatible with the detection of this gene in our Met library." (PMID 18211678, 2008). "Moreover, this regulatory mechanism exists in murine melanoma cells, indicating that NPM1 may have analogous functions in other cancers." (PMID 38243170, 2024). "We observed that ENO1, PARK7, NPM1 and STMN1 genes expression levels were higher in melanoma cells than in melanocytes and in normal fibroblasts." (PMID 29545914, 2018).